PGAM1P5 (phosphoglycerate mutase 1 pseudogene 5)
Gene: Transcribed processed pseudogene on chromosome 12 (95,672,305 to 95,673,068, forward strand). Ensembl gene ENSG00000257150.
Diseases named in the same sentence as PGAM1P5 in open-access papers:
PGAM1P5 is named in the same sentence as 1 disease in open-access papers, as found by Europe PMC text mining. Sharing a sentence is not in itself a finding about the gene and the disease. The quoted sentences say what the papers report.
breast carcinoma (2 papers, 2018 to 2022). "rs60538652, on SIAH2, rs2912774 on FGFR2 and rs67129489 near PGAM1P5/NTN4 were more strongly associated with ER+ or PR+ cases, while rs9383936 near ESR1 was more strongly associated with ER− or PR− breast cancers (Pheterogeneity <0.05)." (PMID 30323354, 2018). "We identified three genome-wide significant V loci: 6q24.1 (ECT2L), 8q24.22 (LINC01591), and 12q22 (PGAM1P5), the first two of which have not previously been associated with MD or breast cancer risk." (PMID 36344993, 2022).